NTAN1 (N-terminal asparagine amidase)
Description:
N-terminal asparagine deamidase that mediates deamidation of N-terminal asparagine residues to aspartate. Required for the ubiquitin-dependent turnover of intracellular proteins that initiate with Met-Asn. These proteins are acetylated on the retained initiator methionine and can subsequently be modified by the removal of N-acetyl methionine by acylaminoacid hydrolase (AAH). Conversion of the resulting N-terminal asparagine to aspartate by NTAN1/PNAD renders the protein susceptible to arginylation, polyubiquitination and degradation as specified by the N-end rule. This enzyme does not act on substrates with internal or C-terminal asparagines and does not act on glutamine residues in any position, nor on acetylated N-terminal peptidyl Asn.
Synonyms: PNAA; PNAD
Tractability: PROTAC: its protein half-life has been measured.
Gene: Protein-coding gene on chromosome 16 (15,037,854 to 15,056,079, reverse strand). Ensembl gene ENSG00000157045.
Subcellular location: Cytoplasm
Subcellular location (Human Protein Atlas): Nucleoplasm; Golgi apparatus
Gene Ontology:
Molecular function: protein binding; protein-N-terminal asparagine amidohydrolase activity
Biological process: ubiquitin-dependent protein catabolic process
Cellular component: cytoplasm; nucleus
Genetic constraint (gnomAD): Loss-of-function variants: 7 observed, 7.8 expected, observed/expected ratio (o/e) 0.9, 90% interval 0.51 to 1.63. That is too few expected variants to judge how well the gene tolerates losing a copy. Missense variants: 111 observed, 133.32 expected, observed/expected ratio (o/e) 0.83, 90% interval 0.71 to 0.98. Synonymous variants: 52 observed, 54.13 expected, observed/expected ratio (o/e) 0.96, 90% interval 0.77 to 1.21.
Homologues: Orthologues: chimpanzee NTAN1 (99% identical), rabbit NTAN1 (93% identical), pig NTAN1 (93% identical), guinea pig NTAN1 (92% identical), mouse Ntan1 (92% identical), dog NTAN1 (81% identical), rat Ntan1 (71% identical), macaque NTAN1 (58% identical), tropical clawed frog ntan1 (58% identical), Drosophila melanogaster Ntan1 (38% identical).
Diseases named in the same sentence as NTAN1 in open-access papers:
NTAN1 is named in the same sentence as 44 diseases in open-access papers, as found by Europe PMC text mining. Sharing a sentence is not in itself a finding about the gene and the disease. The quoted sentences say what the papers report.
schizophrenia (6 papers, 2013 to 2022). A major psychotic disorder characterized by abnormalities in the perception or expression of reality. "Memory and social behavior disturbances in mice and cancer and schizophrenia in humans have been linked to the Ntan1 gene." (PMID 36042338, 2022). "NTAN1 has also been associated with schizophrenia, repeating a broader pattern of convergence between tissue FAs and cognitive function." (PMID 29652918, 2018).
viral infection (2 papers, 2017 to 2018). "Together, these data indicate that viral infection induced the decrease of NTAN1 protein level in a post-transcriptional manner." (PMID 29231806, 2017). "The future study by us or others should uncover how viral infection induces the ubiquitin-independent NTAN1 degradation." (PMID 29231806, 2017). "Our current study found that viral infection can induce NTAN1 degradation, resulting in the suppression of the N-end rule pathway and subsequent evasion of apoptosis." (PMID 29231806, 2017). "As we have found that viral infection promoted the degradation of NTAN1, we ought to investigate which protein degradation pathway(s) are involved in this process." (PMID 29231806, 2017). "Consequently, in the context of viral infection, the partial restoration of NTAN1 expression significantly promoted apoptosis and the relative caspase activity in cells." (PMID 29231806, 2017). "It would be intriguing to find out how viral infection induces the degradation of NTAN1." (PMID 29231806, 2017). "Viral infection promotes the degradation of NTAN1 via the proteasome pathway." (PMID 29231806, 2017). "In addition, we examined the effect of viral infection to exogenously expressed NTAN1 in cultured cells, and found that the exogenously expressed NTAN1 was also down-regulated during the course of viral infection." (PMID 29231806, 2017). "Because the proteasome degradation pathway is usually dependent on polyubiquitylation, we next asked whether viral infection induces the polyubiquitylation of NTAN1." (PMID 29231806, 2017). "In addition, viral infection can induce multiple intracellular signaling pathways, which may induce NTAN1 degradation." (PMID 29231806, 2017). "Interestingly, we found that blocking protein synthesis by CHX before viral infection abolished the effect of DCV to induce NTAN1 degradation, indicating that viral protein synthesis and/or viral replication within infected cells, but not the input viral components, are responsible for this process." (PMID 29231806, 2017). "The results show that, during viral infection, the NTAN1 protein levels could be restored by either MG-132 or lactacystin treatment, suggesting that the proteasome pathway is involved in virus-induced degradation of NTAN1." (PMID 29231806, 2017). "Moreover, we uncovered that the viral infection could induce the degradation of NTAN1, which catalyzes the N-terminal Asn deamidation of the cleaved, smaller DIAP1." (PMID 29231806, 2017). "Interestingly, viral infection promoted the accumulation of NTAN1 after 12 h.p.i., which might be a combined effect of both the degradation of NTAN1 protein and up-regulation of NTAN1 mRNA in the later stage of viral infection." (PMID 29231806, 2017). "Consistent with our previous observation that the cleaved DIAP1 accumulation is dependent on the inhibition of NTAN1-mediated deamidation step, our data show that viral infection induced the gradual decrease of the protein level of NTAN1 but not ATE1." (PMID 29231806, 2017). "Interestingly, the mRNA levels of NTAN1 and ATE1 are both up-regulated during the same time course of viral infection." (PMID 29231806, 2017). "Similar with that of DIAP1, while viral infection immediately after CHX addition did not accelerate NTAN1 depletion (lanes 1–2 vs. 3–4), viral infection before CHX addition significantly promoted NTAN1 degradation rate when compared with that in non-infected cells (lanes 1–2 vs. 5–6)." (PMID 29231806, 2017). "On the other hand, like NTAN14KA, NTAN1K186A is resistant to degradation in the absence of viral infection (lanes 1 vs. 4), indicating that K186 is most responsible for the ubiquitylation-dependent degradation of NTAN1 in the absence of viral infection." (PMID 29231806, 2017). "Moreover, our results showed that NTAN1WT but not NTAN14KA can be polyubiquitylated, while the polyubiquitylation of NTAN1 was not affected by viral infection." (PMID 29231806, 2017).
viral infection (continued). "Interestingly, recent work on flies has shown that that viral infection elicits an elevation of caspase-generated Drosophila inhibitor of apoptosis 1 (DIAP1), a target substrate of the Arg/N-end rule in flies, by invoking the targeted proteasomal-degradation of N-terminal amidohydrolase 1 (NTAN1)." (PMID 30384441, 2018).
atherosclerosis (1 paper, 2024). A disease characterized by the build-up of fatty material and calcium deposition in the arterial wall resulting in partial or complete occlusion of the arterial lumen. "In genetically predicted levels, higher expression of ANXA5, CCDC71L, MED8, MRAS, MRPS6, NTAN1, and SLA5A3 was positively associated with atherosclerosis risk." (PMID 39766313, 2024).
blood coagulation disorders (1 paper, 2025). "MYC exhibited strong associations with blood coagulation disorders, thrombotic microangiopathies, and thrombophilia, while NTAN1 was enriched in hematologic pathologies such as thrombocytopenia and hemolytic anemia." (PMID 41210882, 2025).
meningioma (1 paper, 2020). A generally slow growing tumor attached to the dura mater. "Among the 2N patients, we detected six genes (POLR3F, SEC23B, ZNF133, C16orf45, RRN3, and NTAN1) which were overexpressed after irradiation and were duplicated in the genome of ALL patients with the second independent cancer being either meningioma or thyroid carcinoma." (PMID 32577795, 2020).
Parkinson disease (1 paper, 2025). A progressive degenerative disorder of the central nervous system characterized by loss of dopamine producing neurons in the substantia nigra and the presence of Lewy bodies in the substantia nigra and locus coeruleus. "NTAN1-associated GSEA revealed enrichment in 122 pathways, with the top five pathways comprising ribosome, “oxidative phosphorylation,” “Parkinson’s disease,” “Fc gamma R-mediated phagocytosis,” and “thermogenesis”." (PMID 41210882, 2025).
thrombotic disorders (1 paper, 2025). "The CTD identified MYC and NTAN1 as central players in thrombotic disorders, with MYC linked to 62 diseases and NTAN1 associated with 19 diseases." (PMID 41210882, 2025).
infection (4 papers, 2006 to 2017). The state of being infected such as from the introduction of a foreign agent such as serum, vaccine, antigenic substance or organism. "Our current study uncovered that the infection by a picorna-like virus can suppress the N-end rule pathway by inducing the degradation of its key component NTAN1." (PMID 29231806, 2017). "We suggest the existence of a functional, self-regulating node in infection, which contains MyD88, miR-125a-3p, miR-125b-5p and NTAN1." (PMID 28445535, 2017). "In conclusion, our data showed that virus induced the degradation of NTAN1 protein in the early stage of infection, which could lead to the accumulation of caspase cleaved, smaller form of DIAP1." (PMID 29231806, 2017). "In addition, we show Ntan1, which was down-regulated in WT cells, but was not regulated in MyD88-/- BMMs upon infection." (PMID 28445535, 2017).
bacterial infection (1 paper, 2017). "MyD88-dependent regulation of miR-125a-3p may prove to be a mechanism to control antigen stability and epitope generation via NTAN1 and the N-end rule pathway upon bacterial infection." (PMID 28445535, 2017).
NTAN1 also shares sentences with these, for which no sentence is quoted: tumor (35 papers); melanoma (9); cancer (5); fibrosarcoma (2); rheumatoid arthritis (2); Arthritis (1); autism (1); autism spectrum disorder (1); breast carcinoma (1); colitis (1); colorectal carcinoma (1); cutaneous melanoma (1); desmoplastic melanoma (1); diabetes (1); gastric cancer (1); germinoma (1); Intellectual disability (1); juvenile dermatomyositis (1); lung carcinoma (1); lupus (1); lupus nephritis (1); lymphoma (1); metastatic melanoma (1); neurodevelopmental disorder (1); non-small cell lung carcinoma (1); pancolitis (1); pemphigus (1); polymyositis (1); Sepsis (1); Thrombocytopenia (1).
A further 5 diseases each share a sentence with NTAN1 in 1 paper.